PTH (parathyroid hormone)
Diseases named in the same sentence as PTH in open-access papers (continued):
Sharing a sentence is not in itself a finding about the gene and the disease.
endothelial dysfunction (continued). "PTH determined mitochondrial calcium fluxes ([Ca2+]mt) and the mitochondrial calcium uniporter inhibitor Ru360 (10 μM) reduced mROS production and prevented the PTH-mediated endothelial dysfunction." (PMID 30662585, 2018). "The pathophysiology is incompletely understood, though it is hypothesized that elevated circulating parathyroid hormone may induce endothelial dysfunction, contributing to increased vascular tone and blood pressure elevation." (PMID 41257110, 2025). "Although the mechanism is still unclear, it is hypothesized that PTH increases the levels of calcium in blood stream, leading to endothelial dysfunction." (PMID 39064792, 2024). "Our results suggest that Orai1 and the downstream calmodulin/calcineurin/NFATC1/COL1A1 signaling pathway may play an important role in PTH-induced endothelial dysfunction and may be key potential therapeutic targets for preventing or treating SHPT-induced CVD." (PMID 35369318, 2022). "Among the candidate mechanisms triggered by PTH able to induce endothelial dysfunction, we chose to investigate the MAPKs signaling pathways because of the previous evidence on the implication of these pathways in the process and particularly in calcific aortic valve disease." (PMID 35409134, 2022). "In conclusion, a normal reference range of serum phosphorus levels and corresponding elevated PTH values is associated with endothelial dysfunction in non-dialysis CKD patients." (PMID 35903313, 2022). "Orai1 is likely a key mediator in PTH-induced endothelial dysfunction in CVD." (PMID 35369318, 2022). "Further studies will be needed to clarify whether NO, prostaglandins, or endothelial-derived hyperpolarizing factors are involved in the mechanism by which PTH induces endothelial dysfunction." (PMID 35903313, 2022). "In addition, it was reported in the literature that there is a direct link between endothelial dysfunction and PTH." (PMID 36161626, 2022). "Our data, by putting in relationship PTH and endothelial dysfunction, a mechanism of CVR, provide a possible explanation of the discordant observations regarding the increased CVR in vitamin D–deprived populations and the lack of efficacy of clinical trials based on vitamin D supplementation." (PMID 30662585, 2018). "Therefore, our study is innovative in the fact that for the first time we show PTH-induced endothelial dysfunction in terms of responsiveness to vasodilators and angiogenic competence." (PMID 30662585, 2018). "Indeed, vitamin D supplementation can putatively ameliorate endothelial dysfunction induced by PTH, either by its antioxidative properties or by reduction of serum PTH levels over time." (PMID 30662585, 2018). "However, the molecular mechanism by which PTH regulates endothelial cell proliferation and migration and endothelial dysfunction, leading to vascular disease, remains unclear." (PMID 35369318, 2022). "Although the recent studies suggest that PTH could directly induce endothelial dysfunction and contribute to vascular calcification, the effect of this hormone on human valvular endothelial cells and the effect of dysfunctional VEC on VIC osteogenic phenotype remain unclear." (PMID 35409134, 2022). "Elevated phosphate further exacerbates vascular calcification and endothelial dysfunction via the FGF23/Klotho axis and PTH-mediated pathways." (PMID 41166265, 2025). "Literature studies have shown that parathyroid hormone can promote oxidative stress of vascular endothelium, activation of the RAAS system, arteriosclerosis, and endothelial dysfunction." (PMID 36766651, 2023). "The relative contribution of vascular alterations in PTH-induced increased CVR is still debated, but mounting evidence supports the pivotal role of endothelial dysfunction, even in the early phases of chronic exposure to higher PTH levels." (PMID 30662585, 2018).
endothelial dysfunction (continued). "Other parameters of bone metabolism, such as parathyroid hormone (PTH) and osteocalcin, may also affect endothelial dysfunction potentially by oxidative stress." (PMID 37425312, 2023). "Although, SOST levels may be driven by PTH metabolism in CKD, circulating levels correlated with markers of endothelial dysfunction and inflammation, similar to the present study." (PMID 33914733, 2021). "Additionally, serum levels of neuropeptide Y (NPY), parathormone (PTH), and fibroblast growing factor 23 (FGF 23) are commonly increased in CKD and seem to promote endothelial dysfunction in brain microcirculation." (PMID 32664677, 2020). "In fact, vitamin D exposure in our model failed to acutely reduce PTH-induced ROS production, ruling out the possibility that vitamin D can restore endothelial dysfunction due to its weak antioxidant properties." (PMID 30662585, 2018). "Interestingly, PTH chronic treatment induced an increase in VEGF gene transcription, thus suggesting that PTH might have altered angiogenic competence inducing resistance to VEGF, a common feature of endothelial dysfunction." (PMID 30662585, 2018). "However, whether or not the rise of PTH in this phenomenon contributes to worse migraine headaches through NO release and endothelial dysfunction is a matter of debate that needs further study." (PMID 24524078, 2014).
Hyperglycemia (37 papers, 2009 to 2026). An increased concentration of glucose in the blood. "Hyperglycemia causes diuresis and increases phosphorus calcium output, which, in turn, stimulates parathyroid secretion of parathyroid hormone and increases the osteolytic effect, resulting in a reduction in BMD." (PMID 31277108, 2019). "Hyperglycemia may be associated with increased loss of calcium in urine, however due to other regulatory systems, most notably parathyroid hormone, serum calcium is usually maintained." (PMID 38790001, 2024). "The zebrafish model of hyperglycemia-derived bone loss can contribute to the elucidation of in vivo the molecular mechanisms of bone complications as demonstrated by the analysis of advanced glycation end-products (AGEs) and PTH levels in the fish blood." (PMID 31828085, 2019). "Especially, positive responses could be seen in women in the high-risk groups such as those with hyperglycemia, high risk for arteriosclerosis, bone resorption and fracture, and abnormal PTH levels." (PMID 29722549, 2018). "Nowadays, accumulating evidences support that PTH is related to insulin sensitivity and gestational hyperglycemia." (PMID 38590929, 2024). "Our results suggested that the PTH level within the reference range is related to islet β-cell function and hyperglycemia." (PMID 38590929, 2024). "It has also been elucidated in this study that NKA inhibition by PTH and hyperglycaemia is regulated by activation of PLA2, AA and PGE2." (PMID 31010095, 2019). "One of these, the liquiritigenin (LTG), a flavonoid extracted from Glycyrrhiza glabra roots, significantly prevents the onset of the hyperglycemia in adult zebrafish and systemic alterations such as increase of AGEs and PTH levels in the blood." (PMID 31828085, 2019). "Mechanisms proposed to drive bone pathology in diabetic patients include deficiency in the secretion of insulin and insulin-like growth factor 1, impaired regulation of vitamin D and parathyroid hormone, and emergence of hyperglycemia." (PMID 29196931, 2018). "Lower levels of PTH, in both predialysis CKD as well as in HD treated DM patients, have been related to poor glycemic control (hyperglycemia having an inhibitory effect of on PTH cells) or high levels of AGEs inducing suppression of PTH synthesis." (PMID 25965403, 2015). "Another study showed that an oral glucose load that induced hyperglycemia/hyperinsulinemia promoted a significant decline in serum PTH in postmenopausal women." (PMID 26450680, 2015). "Our studies and others show HYP mice have increased serum PTH with hyperglycemia and hypoinsulinemia." (PMID 24839967, 2014). "The dysregulation of PTH due to hyperglycemia could play a role in this finding and warrants further investigation." (PMID 40313432, 2025). "A more straightforward explanation for the lower PTH levels in patients with T2DM could be that inflammation induced by hyperglycemia hinders PTH production." (PMID 40313432, 2025). "Hyperglycemia can damage the tiny blood vessels in the kidneys, accompanied by a decrease in glomerular filtration rate, as the kidneys are the core organ for regulating the balance of calcium, phosphorus, vitamin D, and parathyroid hormone (PTH)." (PMID 41164826, 2025). "Furthermore, hyperglycaemia significantly decreases parathyroid hormone levels, both of which independently contribute to reduced bone remodelling and quality." (PMID 38711110, 2024). "Existing evidence revealed that magnesium level could decrease under hyperglycemia, with a mechanism of reducing the net tubular reabsorption of it and consequently less PTH secretion." (PMID 38590929, 2024). "Instead, some researchers supposed that the hyperglycemia condition leading to lower PTH level." (PMID 38590929, 2024).
Hyperglycemia (continued). "Other alternative treatments to surpass the harmful effect of hyperglycemia on bone repair around implants, such as the use of the parathyroid hormone, mesenchymal-stem-cell therapy, hyperbaric-oxygen management, doxycycline administration and implant-surface modification, have been evaluated." (PMID 35329768, 2022). "Additionally, the interaction of hyperglycemia with parathyroid hormone and the vitamin D system weakens bone turnover in diabetic patients and reduces osteocalcin produced by osteoblasts." (PMID 33579371, 2021). "In line with this concept, hyperglycemia-induced inflammation could inhibit the secretion of PTH." (PMID 38590929, 2024). "Thus, we speculated that the PTH level within the reference range is related to islet β-cell function and hyperglycemia." (PMID 38590929, 2024). "Future studies could explore the anabolic property of PTH in the DM condition when hyperglycemia is controlled with insulin, and immunolabeling or molecular analyses could be performed to further evaluate the possible anabolic activity of PTH and signaling pathways." (PMID 32348445, 2020). "Excess calcium excretion in the setting of hyperglycemia‐induced osmotic diuresis may underlie the observed differences in the association of calcium intake with vBMD between girls with and without T1D in our cohort, as well as the differences in PTH suppression with increasing calcium intake." (PMID 38025039, 2023). "In addition, hyperglycemia leads to a negative calcium balance and subsequent bone demineralization through regulation of the calcium–parathyroid hormone (PTH) axis." (PMID 30459613, 2018).
coronary artery disease (36 papers, 2014 to 2025). "We herein report that in our hospital population, the diagnosis of PTH was significantly and independently associated with stroke, ischemic heart disease, atrial fibrillation, deep vein thrombosis, and pulmonary embolism." (PMID 37959184, 2023). "Recent prospective study identified interactions of vitamin D-related biomarkers with risk of coronary heart disease, showing that 25-OHD levels are inversely associated with coronary heart disease only among subjects with higher PTH levels." (PMID 29088221, 2017). "The association of vitamin D with coronary heart diseases could be via blood pressure, glycemic control, or parathyroid hormone (PTH)." (PMID 33266477, 2020). "Moreover, higher serum concentrations of PTH correlate with worse prognosis in the setting of cardiovascular diseases, and above-physiological PTH levels independently predict higher risk of hospitalizations, cardiovascular events, and all-cause mortality in HF or stable coronary artery disease." (PMID 30662585, 2018). "An amendment was later approved to broaden the study scope, allowing additional analyses of parathyroid hormone levels, ischemic heart disease outcomes, and kidney disease progression using the existing dataset." (PMID 41309361, 2025). "Our research question was the following: Are vitamins A, E, and D deficiencies as well as PTH and TSH level disturbances associated with elevated calcium scores in subjects at risk of coronary artery disease in Saudi Arabia?" (PMID 40507405, 2025). "In conclusion, vitamin D supplementation only represented the significant effect on 25(OH) D3, PTH, WC and fat percentage in subjects with coronary heart disease." (PMID 30093913, 2018). "There is also evidence connecting adverse cardiovascular outcomes, including death and incident coronary artery disease and myocardial infarction, to PTH excess." (PMID 26377856, 2016). "Considering the results of these previous studies and differences in pathophysiology between coronary artery disease and cerebrovascular disease, it is possible that P, cCa, and intact PTH levels impact these 2 types of disease differently." (PMID 25494334, 2014). "This prior study did not examine the associations of calcium and intact PTH with coronary artery disease or cerebrovascular accident." (PMID 25494334, 2014). "Alongside serum 1,25(OH)2D levels, significant factors tied to LVH encompassed age, coronary heart disease, blood pressure, hemoglobin, urinary albumin levels, phosphate, eGFR, CRP, and intact PTH." (PMID 38722953, 2024). "Shorter survival was demonstrated in patients with older age at the beginning of the study, coronary artery disease (CAD), diabetic nephropathy, and lower serum parathyroid hormone (PTH) concentrations." (PMID 28525983, 2017).
fracture (36 papers, 2009 to 2025). "It is accepted that high level of PTH is negatively correlated with BMDs and 1,25(OH)2D3 as well as positively correlated with high risk of bone fracture." (PMID 30459613, 2018). "In fact, it is well known that elevated PTH levels exert catabolic effects on bone and may be implicated in the genesis of bone fragility and hip fractures." (PMID 35742610, 2022). "Prior evidence suggests that lower concentration of PTH observed in patients referring functional dependence might be due to adynamic bone disease, a prevalent cause of pain and bone fractures in MHD patients." (PMID 32680521, 2020). "In 65 postmenopausal women with pelvic fractures, PTH accelerated fracture healing by more than 30% (7.8 weeks in the PTH group compared with 12.6 weeks in the control group) and improved functional outcomes." (PMID 38911851, 2024). "The percentage of PTH levels greater than 65 pg/mL was observed in 47.0 % of patients with a hip fragility fracture." (PMID 35742610, 2022). "According to SUCRA, SERMs (75%) showed higher incidence of hip fracture followed by fluoride, calcitonin, mAb, and BP; while PTH (17.4%) appeared to be the most efficacious drug in preventing new hip fractures." (PMID 34300210, 2021). "Osteoanabolic PTH therapy was recommended to 79 patients suffering from an acute fragility fracture of the pelvis (FFP)." (PMID 31332508, 2020). "Preclinical studies also support the potential for PTH as a treatment for bone fractures, demonstrating PTH-improved quality of the fracture callus, increased bone mineral content and density, and accelerated endochondral ossification." (PMID 28279202, 2017). "The reasons for the differences in these definitions are partially due to the outcomes, for which the defined cutoff levels were different (e.g., bone fracture, parathyroid hormone (PTH) level, cardiovascular (CV) events, and cancer)." (PMID 26075246, 2015). "Moreover, elevated secretion of parathyroid hormone (PTH), decreased BMD, and increased risk of bone fracture is linked to low levels of serum 25 (OH)D." (PMID 36670720, 2023). "The only predictor for hip fracture was elevated PTH (OR = 7.6 (1.5-36.9), p = 0.013)." (PMID 26910625, 2016). "Regarding bone parameters, patients with ACS had a higher frequency of vertebral fracture, lower BMD Z score at the lumbar spine, femoral neck and TBS; and a higher intact-PTH level and urinary calcium-to-creatinine ratio than those with non-functional AT." (PMID 36035657, 2022). "Previous research has shown that teriparatide, a type of synthetic parathyroid hormone, can promote the formation of callus and lead to healing in individuals with delayed or non-healing bone fractures." (PMID 37187628, 2023). "PTH has been well-established as an inducer of osteogenesis in the osteoporotic patient and has been used in the treatment of various bone fractures in both osteoporotic and non-osteoporotic patients." (PMID 35269519, 2022). "Furthermore, this paper constitutes a unique attempt to compare diabetic and nondiabetic elderly patients with hip fractures regarding VD, PTH, hip fracture severity, serum ALB, and BMD." (PMID 40313432, 2025). "None of them had bone fractures in the last 2 yr and the PTH, PINP, and CTX levels were normal." (PMID 38523666, 2024).